MX2 (MX dynamin like GTPase 2)
Diseases named in the same sentence as MX2 in open-access papers (continued):
Sharing a sentence is not in itself a finding about the gene and the disease.
Werner syndrome (1 paper, 2018). "Similar to senescent NHDFs, fibroblasts from a patient with Werner syndrome also showed higher expression levels of the ISGs, IFIT3, OASL, ISG15, Mx2, and IFIT27, even at earlier passages." (PMID 30455980, 2018).
ZIKV infection (1 paper, 2019). "Interferon-stimulated genes (ISG) such as MX2, IFIT1, IFIT3, IFITM1, IFI35, and RSAD2 (Viperin) were significantly upregulated after ZIKV infection." (PMID 30781519, 2019).
infection (146 papers, 2007 to 2026). The state of being infected such as from the introduction of a foreign agent such as serum, vaccine, antigenic substance or organism. "This is also consistent with our previous work demonstrating that MX2-resistance is context dependent and is affected by CA mutations, cell type, cell cycle, and CypA and that MX2 can increase infection of HIV-1 in some contexts." (PMID 39853118, 2025). "Carp from other strains also showed the up-regulation of mRNA encoding Mx2 protein (particularly at day 6 post-infection), but the magnitude of up-regulation was significantly lower on day 11 post-infection." (PMID 37465154, 2023). "Of note, the infection caused significant upregulation in mRNA expression level of interferon-stimulated genes (Isg15, Mx1, Mx2, Irf3, and Irf7) and pro-inflammatory cytokines (Tnf-α, Cxcl-1, and Il-6 genes)." (PMID 37929187, 2023). "We also found that STRS led to increased detection of putative protein-coding genes, including Ly6a2, Cxcl11 and Mx2, which were associated with infection." (PMID 36329320, 2023). "Infection with A. actinomycetemcomitans caused a significant upregulation in the expression levels of Isg15, Mx1, Mx2, Irf3, Irf7, Tlr-2, Tnf-α, Cxcl-1, and Il-6 genes." (PMID 37929187, 2023). "Crucially, we show that diverse effects of CypA and CA mutations on infection, as well as MX2 antiviral activity, can be induced or abolished by altering Nup levels and NPC composition." (PMID 30084827, 2018). "KPNB1 depletion had a smaller effect on HIV-1WT infection in HT1080 cells but caused a large accentuation of MX2 activity." (PMID 30084827, 2018). "MX1(NMX2) recapitulates many of the features associated with MX2-mediated inhibition: infection is blocked prior to nuclear cDNA import, GTPase activity is dispensable for function, and viral substrate specificity is comparable." (PMID 26446602, 2016). "However, an interesting finding is that, by 2 days post-infection, many of the genes associated with upregulation by interferons, such as Mx1, Mx2 and 2’5’ oligoadenylate synthase (OAS) demonstrate high levels of expression." (PMID 22713837, 2012). "We also determined that the RANBP2-Cyp domain affects the requirements for other Nups for infection and MX2 sensitivity." (PMID 39853118, 2025). "The T210K mutation alters the tri-hexamer interface of the CA lattice and affects interactions between the NTD of MX2 and the CA; however, our data indicate that in certain contexts, this reduced binding is sufficient to inhibit infection." (PMID 39853118, 2025). "Similar to the phenotype in RANBP2∆Cyp cells, we observed a ~twofold reduction in infection and a reduction in MX2 sensitivity of HIV-1WT in both RANBP2D3126N and RANBP2D3126N/K3129H cells." (PMID 39853118, 2025). "We next explored the requirements for RANBP2-Cyp for infection of other lentiviruses with distinct MX2 sensitivities from HIV-1." (PMID 39853118, 2025). "We found that HIV-2 was more sensitive to depletion of RANBP2-Cyp than HIV-1 (~4.4-fold infection defect); however, MX2 sensitivity of HIV-2 was only slightly reduced in RANBP2∆Cyp cells." (PMID 39853118, 2025). "Control and RANBP2∆Cyp cells were transfected with siRNA before being split into replicate wells for MX2 induction (via doxycycline addition) followed by infection with HIV-1WT." (PMID 39853118, 2025). "We demonstrated that HIV-1 CA-Cyp domain interactions have small effects on the HIV-1 titer in single-cycle infection assays and affect integration site targeting and MX2 activity in a manner similar to CA-CypA interactions." (PMID 39853118, 2025). "Our results provide clear evidence that TPF downregulates key antiviral and pro-inflammatory genes, including IFN-β, MX2, and IL6, thereby enhancing the susceptibility of cancer cells to VSVΔ51 infection." (PMID 38932212, 2024). "Accordingly, previous studies have reported the induction of IFI47 and MX2 by type 1 IFNs after infection with whole-virion inactivated influenza virus." (PMID 38932312, 2024).
infection (continued). "The number of unique integration sites mapped from a total of 2 to 4 independent infection experiments varied from 925 for the MX2 NLS chimera to 10,530 for C-MYC NLS protein." (PMID 38979149, 2024). "The requirement for GTP binding is also virus-specific, since the K131A mutation abrogated antiviral activity against HIV-2 and SIVmac, while all other MX2 mutants that inhibited HIV-1WT infection also inhibited HIV-2 and SIVmac infection." (PMID 38512975, 2024). "Both the upper and lower airways responded to the infection by all VoCs, but with a tissue-specific inflammatory signature: in the lungs, Mx2, Il-6, Cxcl10 and Il-10 were upregulated for all VoCs, and the highest in SARS-COV-2 Wuhan-infected animals." (PMID 37495586, 2023). "During the course of an infection with CEV genogroup IIa, the mRNA expression of Mx2 was highly significantly up-regulated in koi at 6 and 11 days post-infection compared to control." (PMID 37465154, 2023). "In the nasal turbinates, Wuhan/ΔORF7ab infection also induced a higher expression of Mx2, but also Il-6, Cxcl10, Tnf-α and Il-10." (PMID 37495586, 2023). "As newborn piglets were infected with the porcine epidemic diarrhea virus, the expression of both antiviral genes MX1 and MX2 were highly significantly upregulated and peaked at 24 h post-infection, resulting in an intense inflammatory response." (PMID 37628612, 2023). "Our analyses indicated that despite the presence of baseline inflammation, 2 yr old mice had significantly lower induction of innate immune genes at 2 days post-infection, including Il6, Ccl4, Cxcl10, Rig-I, Irf7, Ifna2, Oas1b, and Mx2." (PMID 36679892, 2022). "Weak induction of Mx2 was already detectable in the spleen one day after infection by luciferase reporter activity, which continuously increased over time." (PMID 36558888, 2022). "U87-MG CD4/CXCR4 cells expressing wild-type MX2 or the S28D, T151D, T343D, or S28D/T151D mutants were challenged with these stocks, and infection was measured at 48 h." (PMID 35880880, 2022). "On day seven post-infection, Mx2 induction reached a level comparable to control mice that were stimulated by intravenous injection of 20 μg polyinosinic:polycytidylic acid (poly[I:C])." (PMID 36558888, 2022). "While known restriction factors such as MX2 likely play a role, a more systematic approach is needed to determine the range of host cell factors at work in microglia cells in the context of infection during an inflammatory state." (PMID 35975998, 2022). "Most noticeably, Nsp1-K164A/H165A infection had least effects on the expressions of proinflammatory markers, such as Mx2, Ifit3, Tlr6, Cxcl10, and Nfkb1." (PMID 36357440, 2022). "The genes Mx2, Irf7, Ddx58 and Stat1gene transcripts were found up-regulated early in the infection (2 and 4 dpi), whereas Ccl5 was up-regulated only at 4 dpi." (PMID 33941622, 2021). "Intrinsic Mx2 levels in some tumor cells that reach the threshold will render resistance or semi-permissivity to oHSV-1 infection." (PMID 34707174, 2021). "Analysis of Mx2 mRNA induction showed that the virus evaded antiviral responses during cell culture infection and persisted over cell passaging." (PMID 32316667, 2020). "The expression of RIG-1, PKR, OAS1, Mx1, and Mx2 were significantly and positively correlated to each other during the entire infection (P < 0.01)." (PMID 32133381, 2020). "The MX2-depleted cells were more permissive to infection, with increases in viral reporter gene expression ranging from 3.0-fold to 12.7-fold for luciferase-encoding HIV-1LTR and a 5.5-fold increase in infectivity observed for eGFP-encoding HIV-1LTR." (PMID 32934084, 2020). "Real-time quantitative polymerase chain reaction was used to detect differences in the expression of the RIG-1, PKR, OAS1, Mx1, and Mx2 genes at various time points post-infection." (PMID 32133381, 2020).
infection (continued). "Expression of the interferon stimulated gene, Mx2 indicated an antiviral response in infected cells which correlated to the viral input concentration at 96 h post infection." (PMID 32922394, 2020). "The highest abundance of Mx2 mRNA transcripts was observed at 30 h post infection with a significantly higher Mx2 mRNA expression than all other time points measured (p < 0.0001)." (PMID 32922394, 2020). "Though these results demonstrate the increased capsid association of wild-type MX2 compared to MX2 (GMX1), we have previously reported that this chimeric protein is as antiviral as wild-type MX2 in single-cycle infection experiments." (PMID 31722207, 2019). "The classical ISGs were strongly induced by CDV-infection with particularly high levels for Isg15, Ifi44l, Isg56, Oas2 and Mx2 (fold change up to 928.35, 419.93, 179.05, 173.57 and 147.59)." (PMID 30939763, 2019). "Infection experiments performed in the presence of competing MX2 Δ1-25 showed that the combined triple-mutant G184S/N260S/Q351E has the weakest antiviral phenotype, with each single mutant having effects that scored as intermediate." (PMID 31722207, 2019). "In other words, MX2 increased infection by the HIV-1N57S mutant when CypA:CA interaction was inhibited." (PMID 30084827, 2018). "While HIV-1N57S infection was unaffected by either CsA or MX2 in HeLa cells, HIV-1N57S was exquisitely sensitive to CsA (~20 fold inhibition) in HT1080 cells." (PMID 30084827, 2018). "Overexpression of human MX2 exhibited an ~18-fold inhibition of HIV-1/GFP infection compared to the luciferase control after either treatment with a non-targeting control siRNA pool or no siRNA treatment, consistent with previous observations." (PMID 30496303, 2018). "Nevertheless, several downstream genes of the type I IFN signaling pathway were elevated, consistent with reports of other New World arenavirus human infection, including Ifi27, Ifi27l2b, Ifi44, Ifi204, Ifit1, Mx1 and Mx2." (PMID 29724035, 2018). "HIV-1N57S was strikingly inhibited by KPNB1 depletion, and the ability of MX2 to reverse CypA induced inhibition of HIV-1N57S infection was abolished by KPNB1 depletion." (PMID 30084827, 2018). "Unlike HIV-1WT, HIV-1G89V infection was modestly reduced (four-fold) upon NUP62 knockdown in HeLa cells, but HIV-1G89V infection was restored by MX2 expression in NUP62 depleted HeLa cells." (PMID 30084827, 2018). "Infection of HUVECs with KSHV in this setting revealed a modest MxB-dependent restriction (26% less infected cells as compared to the control) that was fully released upon MX2 silencing." (PMID 29773792, 2018). "Other genes involved in immune response which were up regulated in all time point of infection were Mpa 21, Mx2, Mx1 Phf11, Tgtp, B2 m and Tap1." (PMID 21371334, 2011). "In order to study the antiviral response against these viruses in VEFs, cells were infected with CPXV, LV, PUUV-Kazan-E6 and TBEV, and levels of mRNA expression for IFN-β and Mx2 were analyzed with Q-PCR at 6, 12, 24, 48 and 96 hours after infection." (PMID 22194969, 2011). "Using these newly developed Q-PCR protocols, levels of IFN-β and Mx2 mRNA were analyzed in response to infection with CPXV, LV, PUUV-Kazan-E6 or TBEV." (PMID 22194969, 2011). "MX2 also modestly enhanced HIV-1WT infection upon NUP62, RAE1, and TNPO1 knockdown." (PMID 39853118, 2025). "However, both HIV-2 and SIVagmTAN infection and MX2 sensitivity were unaffected in CypA-knockout and mutant cells, similar to SIVmac, which does not bind cyclophilins." (PMID 38512975, 2024). "Similarly, only MX2 mutants that inhibited HIV-1WT infection (MX1MX2-NTD and SSS14,17,18AAA) were able to reverse the reduction in HIV-1N57S CA infectivity in the presence of CsA in HT1080 cells." (PMID 38512975, 2024).
infection (continued). "However, as we observed a more pronounced DC activation in ΔrfaE-infected cells, we reasoned that this would likely be caused by the proteins that were more abundant after infection with the H. pylori mutant, which included ISG15, MX1and MX2." (PMID 39288239, 2024). "Interestingly, Wuhan/ΔORF7ab infection induced a different lung inflammatory signature compared to Wuhan or the other VoCs, represented by a higher expression of Mx2 and Ifn-β." (PMID 37495586, 2023). "With genogroup I infection, Mx2 was up-expressed in koi on 6 dpi and in PS on both 6 and 11 dpi." (PMID 37465154, 2023). "Infection levels of MX2 KO and NTC cells were found to be largely comparable." (PMID 34949807, 2022). "Most of the mutations did not impact the ability of MX2 to inhibit infection as measured by challenging U87-MG CD4/CXCR4 cells with a GFP-encoding HIV-1-based vector (HIV-1/GFP) and enumerating the number of GFP-positive cells at 48 h." (PMID 35880880, 2022). "During E30 infection, genes associated with the type I IFN signaling pathway (Isg15, Mx1, Mx2, Sp100, Ifit1, Ifit3, Ifih1, Irf7, Irf9, guanylate-binding proteins 2 [Gbp2], and Stat1) and defense response to viruses (Ddx58, Ddx60, Zbp1, Oas2, Nlrc5, and Eif2ak2) were significantly upregulated." (PMID 36147849, 2022). "In head kidney, Mx2 also showed the strongest and quickest response, with maximum expression at 24 h post-infection, followed by Mx1, which showed a weak response detected at 24 h post-infection." (PMID 36009736, 2022). "Furthermore, all identified infection-associated ISG genes (MX1, MX2, OAS1Y/Z, OAS2, ISG15, IFI6, IFI44 and RSAD2) showed lower expression values in Holstein infected cells relative to Sahiwal." (PMID 35061738, 2022). "Finally, coinciding with these observations, the addition of gefitinib restored the virus-induced upregulation of the downstream IFN-1 gene MX2, which is otherwise suppressed by vanadate in response to VSVΔ51 infection, as determined by qPCR." (PMID 35572196, 2022). "However, the interferon response (IFNβ1, CXCL10, ISG15, MX1 and MX2) was delayed and increased at 48 h post-infection." (PMID 34452468, 2021). "Based on the role in transcriptional and translational interference, MX1 and MX2 upregulation by pOECs could aim to limit Ct propagation and thereby Ct infection within the genital tract." (PMID 34684219, 2021). "Mx2-depleted A172 cells displayed a significant drop in viability (≥ 50%) starting from 48 h post-infection at an MOI of 0.01 and 0.1, a 50% loss of viability was found in Mx2-depleted WIDR cells at 72 h post-infection." (PMID 34707174, 2021). "Moreover, Mx2 and tTA mRNA levels reverted to background levels within 6 and 10 h after infection, respectively." (PMID 33137201, 2020). "Notably, while the GTPase activity of MX2 is dispensable for its restriction of HIV-1, MX2 mutants that are deficient in GTP binding or hydrolysis are unable to block the infection of herpesviruses." (PMID 33322320, 2020). "Additionally, the ability of MX2 to rescue HIV-1N57S infection from inhibition by CsA in HT1080 cells was reduced by NUP93 and NUP205 depletion." (PMID 30084827, 2018). "Moreover, while HIV-1G89V infection was slightly increased by MX2 in unmanipulated HT1080 cells, RANBP2 depletion caused HIV-1G89V to be inhibited by MX2." (PMID 30084827, 2018). "Thus, altering nuclear pore composition via NUP88/214 depletion clearly modified the effect of MX2 on infection in a CA dependent manner, but had little effect on the action of CsA/CypA." (PMID 30084827, 2018). "The fact that the rescue of the HSV titres was not always complete may be due to incomplete silencing of MX2 expression in A549-MxB cells at the time of infection." (PMID 29773792, 2018). "We found that infection with the IFN-sensitive RRV strain resulted in the robust induction of several well-defined ISGs, including those encoding IFIT1/2/3, ISG15, ISG20, RSAD2, and Mx2." (PMID 27128797, 2016).